EPO (erythropoietin)
Diseases named in the same sentence as EPO in open-access papers (continued):
Sharing a sentence is not in itself a finding about the gene and the disease.
Strongyloides infection (1 paper, 2018). "Previous studies have shown that mice deficient in MBP and and EPO are more susceptible to Strongyloides infection." (PMID 29479356, 2018).
sudden cardiac arrest (1 paper, 2014). Unexpected rapid natural death due to cardiovascular collapse within one hour of initial symptoms. "The dose of EPO chosen for the present experiments (1,200 U/kg) was extrapolated from a dose previously used in a study targeting sudden cardiac arrest victims (90,000 U)." (PMID 25365317, 2014).
systemic inflammatory response syndrome (1 paper, 2025). SIRS is a serious condition related to systemic inflammation, organ dysfunction, and organ failure. "Experimental evidence has identified IL-6 as a key regulator that promotes erythropoietin synthesis during systemic inflammatory response syndrome following septic shock in pediatric populations." (PMID 40895306, 2025).
T-cell leukemia (1 paper, 2025). A malignant disease of the T-lymphocytes in the bone marrow, thymus, and/or blood. "Increased level of TAL1 leads to hypersensitivity to erythropoietin, resulting in excessive erythrocytosis, and is the most common molecular abnormality found in human T-cell leukemia." (PMID 40149853, 2025).
Testicular torsion (1 paper, 2013). Testicular torsion is when the spermatic cord to a testicle twists, cutting off the blood supply. "Two groups (groups 4 and 5) received different protocols of erythropoietin administration after testicular torsion/distortion." (PMID 23710369, 2013). "This study was conducted to investigate the protective effect of erythropoietin (EPO) on ischemia/reperfusion related changes after testicular torsion/detorsion." (PMID 23710369, 2013).
thrombotic microangiopathy (1 paper, 2022). The syndromes of microangiopathic hemolytic anemia, thrombocytopenia, and variable signs of organ impairment, due to platelet aggregation in the microcirculation. "Meanwhile, pretreatment with EPO showed protective effects on the microvascular network including glomeruli and peritubular capillaries guarding against the development of thrombotic microangiopathy, as well as markedly decreased inflammation." (PMID 35422072, 2022).
Tricuspid regurgitation (1 paper, 2023). Failure of the tricuspid valve to close sufficiently upon contraction of the right ventricle, causing blood to regurgitate (flow backward) into the right atrium. "In the United States, a study found that the mean tricuspid regurgitation velocity (TRV) was 2.3 m/s in 399 patients with a mean age of 12 years and the study found that higher regurgitation velocity was associated with high Hgb F, which causes hypoxia and increased erythropoietin concentration." (PMID 37020484, 2023).
Visual impairment (1 paper, 2017). "Collectively, these findings suggested the EPO treatment could ameliorate the MNU-induced visual impairments without giving rise to obvious reverse effects." (PMID 28891332, 2017).
tumor (338 papers, 1993 to 2026). "Chiu and coworkers focused on spontaneous preclinical models of hepatocarcinoma with distinct immunotypes and demonstrated that an activated EPO/EPO-R pathway can induce immunosuppression by binding to EPO-R on tumor–associated macrophages." (PMID 41375075, 2025). "Due to the lack of comprehensive clinical data and the limited number of case samples, the relationship between erythropoietin and tumor recurrence risk remains ambiguous." (PMID 39221033, 2024). "It includes five risk factors: the original tumor site, pre-chemotherapy platelet and white blood cell count, hemoglobin levels, the use of erythropoietin, and body mass index." (PMID 38730721, 2024). "Recent studies have begun to uncover a potential association between erythropoietin and other related drug treatments with tumor recurrence and progression." (PMID 39221033, 2024). "Common causes include tumor hemorrhage, malnutrition, chronic inflammation, tumor infiltration of bone marrow, reduction of erythropoietin synthesis, bone marrow suppression caused by cancer treatment among others." (PMID 38144195, 2023). "Accordingly, as is characteristic of HR-deficient cells, MPB1 tumor cells isolated from EPO-GEMM tumors showed reduced induction of Rad51-containing nuclear foci following irradiation compared to MP tumor cells with intact Brca1." (PMID 35082152, 2022). "RCC associated with polycythemia can be caused by the increased production of erythropoietin, either directly by the tumor or by the renal adjacent parenchyma, due to hypoxic events induced by tumor growth and progression." (PMID 36428491, 2022). "Signs related to the general properties of a tumor are pain—depending on tumor location—weight loss, hematuria, and rarely erythrocytosis due to overproduction of erythropoietin." (PMID 33810219, 2021). "On the other hand, high oxygen levels are associated with angiogenesis, erythropoietin production and oxidative stress, all factors also in favour of the tumour." (PMID 33523307, 2021). "The clinicians needed to be cautious about the potential risk of enhancement of tumor growth when applying the high-dose recombinant human erythropoietin in cancer patients." (PMID 34436045, 2021). "Nevertheless, there was one major concern about the risk of potential enhancement of tumor growth by high-dose recombinant human erythropoietin in cancer patients." (PMID 34436045, 2021). "In recent years, EPO treatment is also recommended for patients with malignant tumors of the hematopoietic system, palliative treatment, and tumor-associated inflammation." (PMID 32848738, 2020). "In our study, we found that EPO expression was significantly associated with VM formation, indicating that EPO can not only promote tumor angiogenesis but also facilitate VM formation in CSCC." (PMID 30915348, 2019). "Among those are elevated serum erythropoietin (EPO) levels caused by secretion of the tumor or associated tumor cyst." (PMID 30214643, 2018). "Among those are extramedullary hematopoiesis or secretion of EPO by the tumor itself or its associated cysts as well as genetic mutations of the VHL gene." (PMID 30214643, 2018). "Among these are extramedullary hematopoiesis within the tumors as well as secretion of erythropoietin (EPO) or other hematopoietic factors by the tumor itself or its associated cysts." (PMID 30214643, 2018). "The causative effects of rhEPO and autocrine/paracrine EPO production on tumor progression are poorly understood." (PMID 28418910, 2017). "To determine the clinical relevance of tumor EPO and EPOR expression, we investigated the association of EPO and EPOR expression with several clinical parameters." (PMID 29137269, 2017). "Administration of EPO-NA to xenograft tumor areas significantly decreased the H1819 and H1155 tumor burdens after 15 days and caused a delayed growth of established tumors." (PMID 29137269, 2017).
tumor (continued). "These include genes encoding for vascular endothelial growth factor, erythropoietin and many enzymes involved in angiogenesis and cellular metabolism, which can further modulate the tumor development and confer treatment resistance." (PMID 27880930, 2016). "Disorders of iron metabolism, blood marrow insufficiency or metastases, malnutrition, bleeding at tumor site, catabolism of patients with tumor burden and relative deficiency of erythropoietin all play a role in anemic pathogenesis." (PMID 25085112, 2014). "Hypoxia can activate some invasion- and metastasis-associated tumor genes including erythropoietin, vascular endothelial growth factor (VEGF), and the VEGF receptor Fit-1, enabling the cells to become more invasive and form VM structures in poor conditions." (PMID 25025074, 2014). "Recently, concerns have arisen over the potential of recombinant human erythropoietin (rhEPO) treatment and an association with tumor growth." (PMID 24004818, 2013). "Quantification of two-dimensional tumor growth in window chambers revealed that the proangiogenic effect of erythropoietin was associated with a significant increase in tumor growth by 66% and 42% on days 2 and 4, respectively, compared to controls (P<0.001)." (PMID 17579721, 2007). "Tumor compression and congestion may cause local hypoxia, triggering renal EPO production via HIF-mediated pathways." (PMID 41487860, 2025). "Ectopic erythropoietin (EPO) production by the tumor is considered the main cause." (PMID 41487860, 2025). "However, increasing evidences indicate that the coexpression of EPO and EPO receptors is thought to be associated with tumor cell growth, invasion, and metastasis." (PMID 37746281, 2023). "Hypoxia is a known hallmark of radioresistance; thus, researchers predict that elevated endogenous erythropoietin levels may be used as a hypoxia marker, causing the tumor to become more aggressive and perhaps impairing treatment effects." (PMID 36121548, 2022). "In this way, EPO may activate tumor-associated macrophages in the tumor microenvironment, thereby suppressing the antitumor immune response and subsequently leading to cancer progression." (PMID 35694408, 2022). "Third, although there was no severe adverse event associated with the treatment in the current meta-analysis, the concerns about the risk of potential enhancement of tumor growth by high-dose recombinant human erythropoietin in cancer patients still should be kept in mind." (PMID 34436045, 2021). "There is also some concern that EPO may increase the risk of tumor growth, although the evidence for this is unclear." (PMID 29673379, 2018). "Additionaly, cell death inhibition by TSA-induced HIF-1α might be associated with various target gene expression such as TGF, EPO and so on to control tumor cell growth and survival." (PMID 29416751, 2018). "We then designed top-down experiments to assess the EPO secretion, function, and underlying mechanism using human blood and tumor specimens, primary tumor cell culture, patient-derived tumor xenograft (PDX) mouse model, NSCLC cell lines and xenograft mouse model." (PMID 29137269, 2017). "Although it seems immature to draw conclusions in this direction, a recent observation by Broxmeyer (2011) might suggest a possible role for EPO in the re-organization of the tumor-associated immune response." (PMID 23052842, 2013). "Given the case history, it is difficult to conclude whether EPO was the cause of the recurrent tumour." (PMID 23305401, 2013). "Our data may have particular relevance to cancer subjects as several tumor cell lines have been shown to secret sEpoR and in whom higher doses of erythropoietin have been associated with mortality." (PMID 20169072, 2010). "However, in our opinion, there is an even more significant consequence of the data obtained that draws attention to the potential threat associated with EPO exposure (whether local or systemic) by creating an immunosuppressive tumor environment." (PMID 41375075, 2025).
tumor (continued). "Particularly challenging in this context is a retrospective, biological analysis of tumor samples from head and neck cancer patients showing that variable expression of EPO-R on tumor cells could be associated with a detrimental clinical outcome in patients treated with r-EPO." (PMID 41375075, 2025). "However, from an epidemiological standpoint, it has been reported that EPO/ESAs administration is associated with an elevation of cardiovascular and venous thromboembolism risks in patients and the induction of tumor progression - independently of the type of cancer or the cancer treatment." (PMID 39916952, 2024). "Tumor associated hypoxia could be one of the players of erythropoietin production in tumor cells." (PMID 36699028, 2022). "An increase of the hemoglobin concentration could also be achieved by erythropoietin injections, but clinical studies revealed increased radiation resistance upon erythropoietin, which can be linked to radiation protective erythropoietin-induced signaling in certain tumor cells." (PMID 34154610, 2021). "However, recent findings raise concerns about the use of EPO in cancer patients, which may be associated with tumor progression and poor patient prognosis." (PMID 32015330, 2020). "In addition, recombinant EPO or erythropoiesis-stimulating agents (ESAs) can accidentally stimulate the growth of EPO-R-positive tumors when used for treating tumor-related anemia suggesting the universality and importance of tumor-associated EPO-R expression." (PMID 31752873, 2019). "In addition, aberrant VEGF and EPO expression closely associated with tumor-induced EMH." (PMID 27708244, 2016). "Quantification of EPO protein in ccRCC showed that the loss of HIF1A protein was associated with very low EPO expression, while the HIF1A presence in the tumor indicated a strong upregulation of EPO compared to HIF1A-negative tumors (p < 0.001)." (PMID 40332447, 2025). "Tumor-derived erythropoietin engages its receptor EPOR on TAMs to autonomously establish a non-inflammatory TME in HCC." (PMID 41417432, 2025). "The results of univariate Cox regression analysis showed that there were significant differences in survival between AST, childpugh, tumor size, vascular invasion, BIRC5, EPO and risk groups." (PMID 40458412, 2025). "There is cumulative evidence that r-EPO, as well as endogenous EPO, bind to and activate EPO-R not only on erythrocyte progenitors in the bone marrow but also on tumor cells." (PMID 41375075, 2025). "This suggests that mutation in VHL leads to the initial activation of EPO expression in renal tumors, subsequently enhancing HIF1A activity, and sustained hypoxia is essential for maintaining EPO expression in the tumor microenvironment." (PMID 40332447, 2025). "Yet, accumulating scientific evidence knowledge has highlighted the complex interactions between EPO and tumor biology that extend well beyond its hematopoietic functions." (PMID 41375075, 2025). "Similar inconsistencies have been described: cases with only mildly elevated serum EPO despite positive tumor staining, and even a case of a 5,400 g uterus with high serum EPO but low intratumoral EPO." (PMID 41487860, 2025). "IPA revealed activation of the EPO signaling pathway and inhibition of three other pathways: the tumor microenvironment pathway, the wound healing signaling pathway, and the estrogen receptor signaling pathway." (PMID 41471763, 2025). "In tumors expressing HIF1A, elevated EPO expression contributes to tumor progression by stimulating EPOR and activating downstream signaling pathways, such as JAK2-STAT5." (PMID 40332447, 2025). "Secondary causes of polycythaemia include high erythropoietin (EPO) states, such as hypoxic pulmonary disease (HPD), cyanotic congenital heart disease (CHD), EPO‐secreting tumours and the use of anabolic steroids." (PMID 40589100, 2025). "As a result, EPO produced by tumors can stimulate the EPO/EPOR signaling pathway in macrophages found in a tumor microenvironment (TME)." (PMID 41012526, 2025).
tumor (continued). "Tumor-derived EPO can bind to EPORs expressed on macrophages, inducing an immunosuppressive phenotype." (PMID 41012526, 2025). "Their experimental investigations conducted on breast carcinoma models were unable to demonstrate a positive link between EPO-R expression and the stimulating effects of r-EPO on tumor growth and migration." (PMID 41375075, 2025). "EPO signaling plays a critical role in shaping the tumor immune microenvironment (TME), particularly through its effects on macrophage polarization." (PMID 41012526, 2025). "For instance, EPO has been shown to accelerate the growth of rat tumor xenografts that lack EPO-R, by enhancing angiogenesis in vivo." (PMID 41375075, 2025). "NB tumours can co-express EPO and its receptor, and their expression correlates with tumour angiogenesis, and EPO has been shown to induce mobility and adhesion in NB cell lines." (PMID 41511287, 2025). "A pro-angiogenic ability of EPO sustains an interaction between EPO and the tumor micro-environment (TME)." (PMID 41375075, 2025). "Patients with significant marrow infiltration by tumor cells have a markedly reduced heme synthesis response to erythropoietin and impaired erythropoiesis, leading to premature destruction of RBC precursors." (PMID 40905013, 2025). "Collectively, these findings suggest caution regarding the potential detrimental effects of r-EPO on tumor growth through favored neovascularization processes." (PMID 41375075, 2025). "Drawing inspiration from the erythropoietin (EPO) biosynthetic process, an EPO enhancer has been constructed to impart the EPO-Keap1 plasmid (DNA) with tumor hypoxia-activated functionality, disrupting the redox homeostasis of the TME." (PMID 40428088, 2025). "The putative expression of EPO receptors on tumor cells has raised concerns about a potential role of EPO in promoting tumor progression, although conclusive clinical evidence remains lacking." (PMID 41375075, 2025). "Studies have confirmed EPO mRNA and protein in tumor tissue; expression levels correlate with tumor diameter and vascularity." (PMID 41487860, 2025). "Erythropoietin (EPO) represents another tumor cell-derived mediator that suppresses antitumor T-cell responses in HCC by interacting with the EPO receptor on tumor-associated macrophages." (PMID 40595432, 2025). "The prompt postoperative decrease in serum EPO and hemoglobin, as we observed in our cases and others, strongly supports this theory of functional hormone secretion by the tumor." (PMID 41487860, 2025). "EPO (Erythropoietin) can enhance the survival ability of tumor cells by inhibiting apoptosis and promoting angiogenesis." (PMID 38244584, 2024). "The expression of genes related to EPO and tumour stemness or pluripotency is primarily regulated by HIF-2α, and copper is also involved in angiogenesis." (PMID 39199143, 2024). "As EPOR is expressed on various immune and tumor cells, the interactions between EPO and these cell types requires further study." (PMID 39474425, 2024). "This review delves into the therapeutic challenges of BCA, emphasizing the roles of interleukin-13 receptor α2 (IL-13Rα2) and erythropoietin-producing hepatocellular receptor A2 (EphA2) in tumor progression and resistance." (PMID 38612592, 2024). "The involvement of EPO in cancer development is more complex, involving potential pro- and anti-tumorigenic effects depending on the specific tumor types." (PMID 38542288, 2024). "The production of erythropoietin by the tumor itself has been identified as the most likely mechanism." (PMID 38674198, 2024). "In particular, HIF-1 is known to induce transcription of more than 60 genes, including VEGF and erythropoietin, which assist in promoting and increasing oxygen delivery to hypoxic regions, thus promoting tumor progression." (PMID 39156707, 2024). "Recently, we demonstrated that EPO affects tumor progression by a direct immunosuppressive action on the tumor microenvironment." (PMID 39916952, 2024).